MYD88 (MYD88 innate immune signal transduction adaptor)
Diseases named in the same sentence as MYD88 in open-access papers (continued):
Sharing a sentence is not in itself a finding about the gene and the disease.
viral infection (continued). "Indeed, in TLR9−/− mice, TLR7 can promote sufficient residual pDC IFN-I production to allow a better control of viral infection and an enhanced resistance to viral-induced lethality as compared to MyD88−/− or TLR7−/−TLR9−/− animals." (PMID 21994554, 2009). "Furthermore, at 8 wpi and 16 wpi, heterozygous mice had developed a low level chronic infection at 102–103 foci per spleen, while Myd88 knockout mice exhibited high (106–107 foci per spleen) levels of virus infection." (PMID 19214214, 2009). "In contrast to MyD88 or IRAK-4 deficiencies, which cause severe, multi-organ disease, TIRAP deficiency may present with a milder phenotype and partially preserved immune responses, especially against viral infections." (PMID 41369391, 2025). "In mice deficient in TLR7/9 or Myd88 or depleted of pDCs and infected with viruses, such as MCMV, HSV or DENV, NK cell cytotoxicity, and cytokine production were decreased or even abolished, thus supporting the contribution of pDCs to NK cell activation in vivo during viral infections." (PMID 38777879, 2024). "Thus, MyD88 upregulation impaired the type I IFN response during many viral infections." (PMID 39125989, 2024). "However, in this context, it is also important to note that, during viral infection, a combination of host factor(s), including MyD88, contributes to the innate immune signaling pathways, which can lead to beneficial (friendly) or detrimental (more like friendly fire) outcomes of the IFN response." (PMID 39125989, 2024). "Together with the reports of HHV6 disease in such patients, and the occurrence of severe influenza pneumonia in two patients from our cohort, these data suggest that MyD88- and IRAK-4–deficient patients may be prone to other severe viral infections, perhaps with low penetrance." (PMID 36880831, 2023). "First, human pediatric patients with deficiency in TLR/IL-1R signaling molecules, MyD88 or IRAK-4, are predisposed to pyogenic bacterial infections, including S. pneumoniae, S. aureus, and P. aeruginosa, whereas other types of bacterial, fungal and viral infections are exceedingly rare." (PMID 23209417, 2012). "However, this protein also inhibits expression of several genes encoding proteins that induce synthesis of IFN in response to viral infection, including Rig 1 (aka Ddx58), Mda5 (aka If1h1), Irf7 and Myd88, suggesting that it also blocks the initial production of anti-viral cytokines." (PMID 22912576, 2012). "To investigate when during virus infection UL88 acts to downregulate HCMV-exposure-induced MyD88 expression, we measured MyD88 levels at 3-day intervals after infection." (PMID 40638072, 2025). "For the first time, we integrated these findings and demonstrated that during recombinant virus infection, HMGB1 binds to TLR4 on macrophages, activating the MyD88-NFκB-NLRP3 (ASC) pathway and inducing M1 polarization." (PMID 40082916, 2025). "In wild-type mice, Yinqiao powder significantly decreases the expression levels of TLR7, MYD88, IRAK4, and NF-κB, which are elevated during viral infection." (PMID 39897040, 2025). "Certainly, viral infection first activates PRR(s) located on the cell surface, and then transmits signals to MyD88 through ligand binding, which is also an important mechanism for virus triggered inflammation." (PMID 40067802, 2025). "In contrast, MyD88 and IFNAR1 KO mice exhibited resistance to a lethal dose (1×105 pfu) of the Delta P80 virus infection." (PMID 39652608, 2024). "Moreover, efficient recognition and killing of infected cells by NK cells could compensate for Myd88 deficiency but not Ifnar1 deficiency, consistent with enhanced susceptibility to viral infections in patients harboring NK cell defects." (PMID 38777879, 2024). "DEGs unique to infected cells mapped to host defense (MYD88, C3, CASP4, JAK2, and OSM), viral infection (RNASE6 and SVVORFs), and protein synthesis (RPL18 and RPS16)." (PMID 38887303, 2024).
viral infection (continued). "Given that the protein level of MyD88 expression remains unaltered following HSV-1 infection, viral infection leads to an elevation in the mRNA levels of TLR2 and TLR3, an effect that can be mitigated by PVE30." (PMID 38185640, 2024). "It interacts with myeloid differentiation primary response 88 (MyD88) and mitochondrial antiviral-signaling protein (MAVS), which are pivotal adaptor proteins involved in innate immune signaling pathways activated by viral infections." (PMID 38747288, 2024). "This review presents future directions for MyD88- and Gal3-targeted antiviral drug discovery, highlighting the role of SARS-CoV-2 or any future COVID-19-like emergent viral diseases in balancing host immunity." (PMID 39125989, 2024). "In general, the activation of both MyD88 and NF-κB is essential for TLR2-mediated inflammatory responses following viral infection." (PMID 36171749, 2022). "After a viral infection, there is a rapid redistribution of MyD88 to the endosomal compartment, where the TIR domains of TLR8 phosphorylate MyD88." (PMID 35215078, 2022). "The expression levels of TLR7, Myd88, and NF-κB p65 mRNA were determined to study the effect of FTA on the TLR7 signaling pathway of viral infection." (PMID 35733131, 2022). "Berberine also suppressed the viral infection-induced up-regulation of the TLR7 signaling pathway, such as TLR7, MyD88, and NF-κB." (PMID 34630083, 2021). "The levels of TLR3, TLR7, myeloid differentiation primary response 88 (Myd88), and RIG-I were up-regulated due to viral infection, which were decreased, as expected, in the presence of 3D, oseltamivir, or ribavirin." (PMID 33670217, 2021). "The results of the current study indicate that both TLR3- and MyD88-dependent signaling play an important role in shaping the development of innate immune responses and may help explain the complications of bacterial and viral infections in chronic oral inflammation." (PMID 32824595, 2020). "Although TLR3 is identified as a major MyD88-independent PRR for the induction of type-1 IFN, in response to different viral infections, the role of TLR3 in bacterial infections is poorly understood." (PMID 32824595, 2020). "A previous study on virus infection-induced seizures showed that MyD88 deficiency led to a nonsignificant reduction in the incidence of SE in mice infected with Theiler’s murine encephalomyelitis virus, whereas the effect of MyD88 deficiency itself on SE was not documented." (PMID 30112701, 2018). "Virus infection induced significant increase in the mRNA levels of TLR7, MyD88, IRAK4 and NF-κB in wild type mice compared to blank control (P < 0.001)." (PMID 30151032, 2018). "We further demonstrated that virus infection increased protein expression levels of TLR7, MyD88, IRAK4 and NF-κB with western blotting, while Oseltamivir, Guizhi-and-Mahuang decoction, Yinqiao powder decreased their expression." (PMID 30151032, 2018). "Viral infections induce a characteristic activation of immune response, e.g., TLR3, 4, 7, 8, 9 in the endosome and their downstream targets, especially MyD88." (PMID 28861088, 2017). "Complete MyD88−/− mice have reported defects in the induction of humoral responses using OVA and LPS in Complete Freund’s adjuvant, live virus infections, with inactivated influenza virus, or with OVA/PorB as we have previously demonstrated." (PMID 28316602, 2017). "pDCs represent by far the major type I IFN-producing cells in vivo in response to viral infections, during autoimmunity and even bacterial infection, through TLR7/ and TLR9/MyD88 sensing of nucleic acids." (PMID 27792766, 2016). "TLR7, MyD88, TRAF6, IRAK4 and NF-κB p65 mRNA were up-regulated after virus infection (p < 0.01) while down-regulated after oseltamivir and FTA treatment (p < 0.01)." (PMID 27128889, 2016).
viral infection (continued). "However, whether IFN-I responses are impaired in infected MyD88-/- mice and whether this contributes to their enhanced susceptibility to viral infections had not previously been rigorously examined." (PMID 25954804, 2015). "Following viral infection, the activation of TLR3-mediated MyD88-independent signalling and TLR7-mediated MyD88-dependent signalling leads to the activation of the nuclear transcription factor NF-κB, resulting in the upregulation of proinflammatory factor expression." (PMID 39897040, 2025). "UL88 alone was sufficient to downregulate MyD88 in the absence of virus infection and was required for this downregulation in the context of infection." (PMID 40638072, 2025). "We demonstrate that MyD88 and type I IFN signaling exacerbates the Delta P80 virus infection." (PMID 39652608, 2024). "Our studies revealed the mechanisms underlying the impairment of antiviral type I IFN signaling and the role of upregulated MyD88 (MyD88–IRF interactions), which likely influence alternative MyD88-independent immune signaling pathways during many viral infections." (PMID 39125989, 2024). "Further, while the recruitment and activation of MyD88 and TRIF are critical for a robust innate immune response, these two proteins have been shown to be activated after viral infection and often exert an opposing effect on the expression of inflammatory genes." (PMID 39125989, 2024). "Moreover, the upregulation of expression of TLR7, MyD88, IRF7, IRAK4, TRAF6, and TRAF3 induced by viral infection were significantly suppressed under FFYH treatment both in vitro and in vivo." (PMID 37089926, 2023). "These phenomena could be due to the fact that DVP-1 strengthened the organic immunity by stimulating the TLR4/MyD88/NF-κB signaling pathway by which more cytokines, such as IL-1β, IL-4, IL-6, and TNF-α, were generated and released before the viral infection." (PMID 36177044, 2022). "In addition to the viral process related signaling, the GO analysis identified many potential viral infections related signaling pathways, e.g., MAPK, JNK, STAT, ERK1/2, MYD88 and Toll like receptor signaling pathways." (PMID 33413329, 2021). "Recent report on therapeutic inhibition of MyD88 in restoring host antiviral type IFN response in MyD88-inpedendent pathways has been described in vitro with several viral infections and also in mice models of viral diseases." (PMID 33834387, 2021). "However, during many viral infections, for example, Coxsackievirus B3, VEEV, or Marburg virus infection which also utilizes RLR signaling pathways, a significant upregulation MyD88 has been observed." (PMID 33834387, 2021). "This MyD88-IRF-7 pathway was found to operate mainly in pDCs, and is largely responsible for the rapid induction of high levels of type I IFN, following the activation of TLR7/8/9 by nucleic acids during viral infection." (PMID 32373120, 2020). "Interestingly, viral infections occurred in the fetal membranes that secreted MIP-1β and RANTES, in response to poly I:C, via MyD88 signaling." (PMID 32824595, 2020). "In particular, they upregulated transcription of the genes involved in cellular response to viral infection and foreign genetic material, such as RIG-I (DDX58), OAS1, MYD88, RNASEL, PKR (EIF2AK2), as well as interferon-dependent transcription factor STAT and IRF families." (PMID 29986702, 2018). "However, MyD88 was up-regulated upon viral infection, because all other members of TLRs family, except for TLR3, can be activated by MyD88 dependence." (PMID 30151032, 2018). "The results showed that the expression levels of TLR7, MYD88, IRAK4 and NF-κB were remarkably up-regulated upon viral infection, and Guizhi-and-Mahuang decoction and Yinqiao powder could down-regulate their expressions in wild type mice." (PMID 30151032, 2018).
viral infection (continued). "In this stable cell line, NF-κB activity was enhanced by EV71 infection and R848 stimulation, but attenuated in the presence of shTLR7, shMyD88, shIRAK1, shNF-κB p65, and shNF-κB p50, confirming that TLR7, MyD88, and IRAK1 are involved in the activation of NF-κB during viral infection." (PMID 28854257, 2017). "Lack of intrinsic MyD88 signaling during viral infection enhanced apoptosis of effector CD8+ T cells (despite normal Bcl-xL expression) without affecting proliferation." (PMID 26367276, 2015). "Synthetic ligands mimicking microbial ligands of TLR9 and TLR7 have been generated and used to dissect the molecular pathway downstream of Myd88, but these artificial molecules did not exactly reproduce the signaling cascades induced in pDCs during in vivo viral infections." (PMID 38777879, 2024). "IRAK4- or MyD88-deficient patients suffer from bacterial or viral infections but not from autoimmune diseases, suggesting that targeting of IRAK4 and MyD88 may prevent autoimmunity in humans." (PMID 34572504, 2021). "Furthermore, while recruitment and activation of the adaptor proteins MyD88 or TRIF are critical for the induction of innate immunity, activation of both MyD88 and TRIF has been demonstrated following virus infection and often induces an opposite effect on inflammatory gene expression." (PMID 33834387, 2021). "Understanding the mechanisms leading to the disruption of the architecture of lymphoid organs early during viral infections in mice and how MyD88 or NK cell responses can prevent this process could open novel avenues to treat viral infections in humans." (PMID 25954804, 2015). "However, patients with MyD-88 and IRAK-4 deficiency show no impaired defense against viral infections, due to their normal functional natural killer cells as well as their retained ability to signal through TLR-3/-7/-9 and other non-TLR viral receptors." (PMID 25528552, 2014). "Myd88 −/− mice showed an enhanced susceptibility to rMA15 virus infection in C57/B6 mice and RAG1−/− mice showed no increased morbidity and mortality from rMA15 virus infection, viral replication in the lungs was detectable through 28 days post-infection." (PMID 20386712, 2010). "Moreover, MyD88 has been reported to be required for the maturation of functional Tip-DCs from Ly-6Chi monocytes, which suggests that functional maturation of Tip-DCs could be facilitated by TLR recognition of viral infection." (PMID 29760708, 2018). "Our data indicate that MyD88 is rapidly upregulated after exposure to HCMV, but that virus infection is not required for this upregulation." (PMID 40638072, 2025). "The expression of MyD88 significantly induced IFN-β transcription, which was inhibited by M2-2 protein expression in the absence of viral infection, suggesting a role of M2-2 in MyD88-mediated signaling." (PMID 24618691, 2014). "Because no detectable modulatory effect on the part of MyD88 and TRIF were observed during single-PEDV infection, the up-regulation effect of TRAF6 may be the result of direct viral infection." (PMID 36376395, 2022). "Other cytokines such as IFN-α or other host factors or signaling elements, e.g. MyD88, may compensate for the lack of endogenous IL-12 or IFN-γ in determining Th cell differentiation in such viral infections." (PMID 18990205, 2008). "Colocalization analysis of TLR9 and MyD88 to ER or endosomes in JIMT-1 CD44+/CD24−/low CICs showed that neither TLR9 nor MyD88 fully reaches endosomes in 4 h and 6 h respectively, whereas in the CD44−/CD24− non-CIC population localization became endosomal upon virus infection." (PMID 21079774, 2010).
lymphoma (96 papers, 2012 to 2026). A malignant (clonal) proliferation of B- lymphocytes or T- lymphocytes which involves the lymph nodes, bone marrow and/or extranodal sites. "Our integrative NGS panel, covering the most recurrent lymphoma biomarkers, clearly demonstrated a higher ctDNA detection rate compared to relying solely on MYD88 and CD79B variants." (PMID 40346678, 2025). "CD79B mutations frequently co-occurred with MYD88 L265P, with 71% (n = 12) of CD79B-mutated lymphomas harboring a MYD88 mutation (p < 0.05)." (PMID 41295250, 2025). "In line with this, we evaluated an additional series of 71 extranodal DLBCL samples by AS-PCR and found a prevalence of the MYD88 p.L265P mutation of 45%, in sharp contrast to the less than 10% of nodal lymphoma cases that exhibited the mutation." (PMID 40067847, 2025). "Recently, PCNSL has been related to the so-called ‘MCD’ subgroup, which is a genetic subset of lymphomas with gain-of-function mutations in both MYD88 L265P and CD79B." (PMID 38730692, 2024). "The MYD88 L256P somatic mutation that is present in an estimated 95% of patients with WM has helped greatly in differentiating the two lymphomas." (PMID 37458281, 2024). "Using molecular dynamics simulation, these authors demonstrated that mutated residues of MYD88 L265P and other lymphoma-associated mutants are shielded and likely affect interacting residues through an allosteric effect." (PMID 37591861, 2023). "Preclinical data suggest that the IRAK4 inhibitor emavusertib results in lymphoma cell death in vitro with MYD88-mutated indolent B-cell lymphomas as a single agent and as a combination partner with BTK or PI3K inhibitors in unselected populations." (PMID 38068428, 2023). "The presence of mutations in earlier progenitors opens up new lines of investigation, which should be extended to other MYD88-mutated lymphomas." (PMID 35628381, 2022). "Somatic mutations in MYD88, including the most common L265P, have been associated with the development of certain types of lymphoma." (PMID 35628381, 2022). "Thirty‐four of 113 (30%) lymphomas harbored both MYD88 and CD79B mutations and were found in the breast (2/4; 50%), CNS (13/26; 50%), ENT (10/28; 36%), skin (5/16; 31%), testis (2/7; 28%), stomach (1/10; 10%), and PMBL (1/12; 8%)." (PMID 36051079, 2022). "SYK can also be activated by the hematopoietic cell kinase (HCK) in MyD88-mutated lymphoma cells, and, at the same time, HCK can be triggered either by mutated MyD88 directly or through IL-6." (PMID 35628381, 2022). "Pirtobrutinib inhibits growth and can trigger the apoptosis of MyD88-mutated lymphoma cells in a highly selective manner, thus improving their efficacy and tolerance." (PMID 35628381, 2022). "On the other hand, a point mutation within TIR domain of MyD88 can lead to the constitutive activity of MyD88 that is a survival signal for proliferation in DLBC lymphoma cells, particularly in Waldenstrom’s macroglobulinemia." (PMID 35069570, 2021). "Previous studies have shown that MYD88 gene mutations are highly prevalent and support lymphoma growth through NF-κB signaling in PCNSL 10-13." (PMID 33664848, 2021). "Since SYK activation is directly caused by mutated MYD88 and mediates its downstream STAT3 and AKT signaling, we next sought to clarify the importance of SYK in supporting cell growth and survival in MYD88-mutated lymphoma cells." (PMID 32005797, 2020). "The findings provide a framework for the clinical investigation of ibrutinib with SYK inhibitors in MYD88-mutated lymphomas." (PMID 32005797, 2020). "Targeting SYK in combination with ibrutinib produces synthetic lethality, providing a framework for the clinical investigation of ibrutinib with SYK inhibitors in MYD88-mutated lymphomas." (PMID 32005797, 2020). "Cell viability analysis showed that combining ibrutinib and SYK inhibitors triggered synthetic killing of MYD88-mutated lymphoma cells." (PMID 32005797, 2020).